PYCR2 (pyrroline-5-carboxylate reductase 2)
Diseases named in the same sentence as PYCR2 in open-access papers (continued):
Sharing a sentence is not in itself a finding about the gene and the disease.
tumor (14 papers, 2016 to 2026). "GSEA was used to assess the correlations between PYCR2 expression and tumor-associated pathways in CRC through analyzing the TCGA CRC datasets (41 normal samples and 473 CRC sample)." (PMID 34512817, 2021). "This activation triggers the transcriptional upregulation of the metabolic enzyme pyrroline-5-carboxylate reductase 2 (PYCR2), a key node in proline biosynthesis that facilitates tumor growth." (PMID 41930328, 2026). "This LINC02878/ZNF282/PYCR2 signaling cascade drives proline anabolism, thereby fueling tumor metabolic reprogramming and fostering aggressive malignant progression in CRC." (PMID 41331125, 2025). "Mechanistically, LINC02878 binds to the ZNF282 to activate PYCR2 expression, thereby enhancing proline biosynthesis and driving tumor aggressiveness." (PMID 41331125, 2025). "In this regard, we obtained reproducible outcomes from two different CRC cell lines, HCT116 and SW620, finding that inhibiting PYCR2 inhibits cell survival, anchorage-independent growth, and invasive mobility, as well as in vivo tumor growth." (PMID 37508547, 2023). "Tumor size in mice receiving the PYCR2-KD cells was considerably lower compared with mice receiving the control cells." (PMID 37508547, 2023). "Further analysis of the protein expression using CPTAC (Clinical Proteomics Tumor Analysis Consortium) showed a similar significant upregulation of PYCR2 expression in CRC." (PMID 37508547, 2023). "For the subcutaneous xenograft tumor growth assay, athymic/nude mice (6–8 weeks old) were injected with a single-cell suspension (1 × 106/100 μL) of control and PYCR2-KD SW620 cells under the dorsal flank." (PMID 37508547, 2023). "An underlying dependence of CR tumor cells for energy metabolism pathways such as enhanced expression of GLDC, ACC, ASNS, FDFT1, UGDH, PYCR2, etc was noted." (PMID 27470985, 2016). "Thus, our work defines C1orf35 as a dual-function oncoprotein that promotes CRC progression by coordinately enhancing tumor-intrinsic growth via the c-Myc/PYCR2 axis and fostering an immune-suppressive niche." (PMID 41930328, 2026). "Moreover, analysis of TCGA-COADREAD data revealed that PYCR2 expression was also significantly elevated in tumor tissues, advanced-stage cases, and among deceased patients." (PMID 41331125, 2025). "Several studies have indicated that overexpression of PYCR1 and PYCR2 accelerates tumor growth." (PMID 39125668, 2024). "Given that PYCR2 inhibition resulted in the significant inhibition of the proliferation and invasive motility of CRC cells, we next determined the effects of PYCR2 loss on in vivo tumor growth." (PMID 37508547, 2023). "Six critical metabolic enzymes within four pathways were present at higher levels in tumor compartments than in normal tissue: the pyrroline-5-carboxylate reductase PYCR2, glutaminase, uridine phosphorylase UPase1, fatty acid synthase, and ornithine decarboxylase." (PMID 36376874, 2022). "Further RRM2, GMPS, BCAT1, PYCR2, and NEU1 are identified in tumor tissue as actionable candidates for prevention." (PMID 40290517, 2025). "Three isoforms, PYCR1, PYCR2, and PYCR3, existed and played significant regulatory roles in tumor initiation and progression." (PMID 39125668, 2024). "In both brain and tumor samples, relative mRNA expression of key proline cycle enzymes, that is, POX/PRODH, PYCR1, PYCR2, and PYCR3, were evaluated, along with the expression of genes associated with ECM degradation, i.e., PEPD, MMP-2, and MMP-9." (PMID 38275897, 2024). "The genetic inhibition of PYCR2 inhibited the tumorigenic abilities of CRC cells and in vivo tumor growth." (PMID 37508547, 2023). "Among others, it identified pyrroline-5-carboxylate reductase 2 (PYCR2) and ornithine decarboxylase (ODC), rate-limiting enzymes in proline and polyamine biosynthesis, respectively, as markers of tumor proliferation." (PMID 34294128, 2021).
tumor (continued). "Examination of the levels of all pathway proteins showed that mitochondrial proline biosynthesis pathway proteins, PYCR1, PYCR2 and ALDH18A1, are higher in tumor samples relative to normal tissue before and after treatment." (PMID 32960509, 2020). "In tumor tissue, these pathways were significantly deregulated regarding gene and protein expression in two independent datasets, including actionable targets RRM2, GMPS, BCAT1, PYCR2, and NEU1." (PMID 40290517, 2025). "The expression of PYCR2 was positively correlated with TMB in 6 cancer types and positively correlated with MSI in eight cancer types but negatively correlated with TMB in four tumor types and MSI in three tumor types." (PMID 39125668, 2024). "Therefore, expression of POX/PRODH, PYCR1, PYCR2, PYCR3, and PEPD was evaluated in both tumor and brain." (PMID 38275897, 2024). "Additionally, mitochondrial pyrroline‐5‐carboxylate reductase 2 (PYCR2) and 3‐hydroxy‐3‐methylglutaryl‐CoA synthase 1 (HMGCS1) protein levels were significantly reduced in these tumor lysates." (PMID 35929764, 2022). "Out of the three studied PYCR isoforms, only PYCR1 turned out to be uniformly upregulated in tumor tissue, which was corroborated by the three assays performed—RT-PCR, Western immunoblot and IHC; minor differences noted in PYCR2 and PYCR3 did not yield statistical significance." (PMID 38275897, 2024). "Thus, PYCR2 interference may directly regulate energy metabolism or increase ROS and disrupt redox homeostasis, thereby activating AMPK signaling and inhibiting tumor initiation and progression." (PMID 37325047, 2023). "For additional validation showing that an increase in cancer cell apoptosis in response to PYCR2 inhibition may be responsible for the inhibition of tumor growth, we performed immunoblot analysis using lysates from HCT116 and SW620 control cells and PYCR2-KD cells." (PMID 37508547, 2023).
cancer (11 papers, 2016 to 2025). A tumor composed of atypical neoplastic, often pleomorphic cells that invade other tissues. "Increase in cancer staging and metastasis was also associated with an increase in PYCR2 expression levels." (PMID 34512817, 2021). "Intriguingly, the results of GSEA of TCGA datasets showed that the cancer-promoting effect of PYCR2 was closely associated with the PI3K/AKT/mTOR pathway in CRC." (PMID 34512817, 2021). "Our knockdown studies confirmed the relevance of PYCR2 in proliferation, colony formation, and migration, all key cancer features, underscoring its role as an actionable candidate during hepatocarcinogenesis." (PMID 40290517, 2025). "Recent studies highlight that PYCR2, a key enzyme in proline biosynthesis, is frequently overexpressed in cancers, and closely related to the malignant progression and poor prognosis of various cancers, including CRC." (PMID 41331125, 2025). "Immunoblotting using control and PYCR2-inhibited SW620 cells showed similar downregulation in cancer stem cell markers." (PMID 37508547, 2023). "An immunoblot analysis of EpCAM, E-cadherin (known epithelial cell markers), and vimentin (known mesenchymal cell markers) was performed to determine the effect of PYCR2 upon cancer cell phenotype." (PMID 37508547, 2023). "A similar increase in these proteins in xenograft tumors further supported the role of PYCR2 in promoting cancer cell survival to then promote CRC." (PMID 37508547, 2023). "We also show that PYCR2 impacts the CSC population by regulating cancer cell survival in a MASTL/Wnt-signaling-dependent manner." (PMID 37508547, 2023). "PYCR2 remains the least investigated enzyme for its role in cancer, though recent studies have demonstrated its prognostic significance in cervical; hepatocellular; and, recently, colon carcinoma." (PMID 37508547, 2023). "To further determine the role of PYCR2 in colon carcinogenesis in a true colonic microenvironment, we used an orthotopic xenograft model recently described by our lab, where cancer cells are transplanted into the colonic wall to generate tumors." (PMID 37508547, 2023). "A non-cancer role for PYCR2 in brain abnormalities and neuronal dysfunctions such as hypomyelination, microcephaly, leukodystrophy, and spastic paraplegia has also been reported." (PMID 37508547, 2023). "Among these proteins, Transformer2A (TRA2A) and Pyrroline-5-carboxylate reductase 2 (PYCR2) are closely related to cancer development." (PMID 35669517, 2022). "TRA2A and PYCR2 are highly expressed in several cancer tissues and regarded as oncogenes or biomarkers." (PMID 35669517, 2022). "Transformer2A (TRA2A) and Pyrroline-5-carboxylate reductase 2 (PYCR2) are related to cancer development and are overexpressed in many cancer cells." (PMID 35669517, 2022). "An increasing number of studies have indicated that PYCR2 has an indispensable role in cancer cell proliferation and progression." (PMID 34512817, 2021). "Our data showed that PYCR2 expression is associated with poor prognosis in CRC, and its inhibition promotes cancer cell death; oncogenic growth supports such a hypothesis." (PMID 37508547, 2023). "PYCR2, an enzyme that catalyzes the synthesis of l-proline from Δ1-pyrroline-5-carboxylate (P5C), was reported to promote cancer growth and inhibit apoptosis through multiple approaches, such as regulation of cell cycle and redox homeostasis and promotion of growth signaling pathways." (PMID 35669517, 2022). "Because proline metabolism is catalysed by PYCR2, it was speculated that PYCR2 was a potential molecular target for cancer treatment." (PMID 34512817, 2021). "Further studies revealed that PYCR2 regulates Wnt/β-catenin-signaling in manners dependent on the expression of MASTL and the cancer stem cell niche." (PMID 37508547, 2023).
cancer (continued). "We found a similar significant increase in PYCR2 expression in CRC patients in publicly available databases for Korean (p = 0.000201), French (p = 2.003 × 10−11), and Amsterdam (Amsterdam, p = 0.015) cancer patients." (PMID 37508547, 2023). "Since both E4B and its substrates, TRA2A and PYCR2, are highly expressed in many cancer tissues and cells, we wanted to know whether E4B can degrade TRA2A and PYCR2 efficiently in the same type of cancer cells." (PMID 35669517, 2022).
adenocarcinoma (2 papers, 2021 to 2023). A common cancer characterized by the presence of malignant glandular cells. "A review of the TCGA database revealed that PYCR2 was highly expressed in CRC patients and that high PYCR2 expression was associated with advanced stage, adenocarcinoma, nodal metastasis, and poor survival rate." (PMID 34512817, 2021). "Moreover, PYCR2 was highly expressed in adenocarcinoma than in other histological subtypes (P < 0.01), and its expression increased significantly with increasing nodal metastases (P < 0.01)." (PMID 34512817, 2021). "Taken together, PYCR2 was highly expressed in CRC, especially in adenocarcinoma, and higher PYCR2 expression indicated a more advanced stage, increased nodal metastasis, and a poor survival rate compared to that in CRC patients with low PYCR2 expressions." (PMID 34512817, 2021).
colon (1 paper, 2023). "To further investigate the causal role of PYCR2 in colon carcinogenesis, we genetically manipulated endogenous PYCR2 expression." (PMID 37508547, 2023).
PYCR2 also shares sentences with these, for which no sentence is quoted: bladder cancer (1 paper); gastric cancer (1); genetic disorder (1); liver cancer (1); liver dysfunction (1); Menkes disease (1); metabolic disorders (1); myeloma (1); nasopharyngeal carcinoma (1); neurodevelopmental disorder (1); pancreatic cancer (1); prostate carcinoma (1); pyridoxine-dependent epilepsy (1); Respiratory insufficiency (1); skin cancer (1).